NOTCH1 (notch receptor 1)
Diseases named in the same sentence as NOTCH1 in open-access papers (continued):
Sharing a sentence is not in itself a finding about the gene and the disease.
tumor (continued). "Jagged-1 expressed by tumor cells can induce Notch pathway activation in neighboring cells; Jagged-1 is capable of binding to activated Notch 1, thereby facilitating its expression by counteracting Dll4 activity and amplifying VEGF activity." (PMID 38927059, 2024). "siRNA targeting Notch1 significantly reduces Notch1 expression, thereby inhibiting tumor cell proliferation and migration, inducing cell apoptosis, and exhibiting anticancer effects." (PMID 38866828, 2024). "By increasing the expression of tumor-suppressive microRNA, miR-34a, rhamnetin reduces Notch-1 expression and promotes apoptosis." (PMID 39062967, 2024). "It has previously been shown that DLL4/Notch1 inhibition increases vascularization, leading to unproductive angiogenesis that inhibits tumor growth." (PMID 39095583, 2024). "The increased Notch1 and Jagged‐1 is associated with tumor metastasis and has the ability to enhance the migration and EMT of tumor cells." (PMID 39092293, 2024). "The other high-NRAS cluster, which included tumour cells, exhibited elevated Notch1 and TGFβ signalling." (PMID 39112713, 2024). "Next, the detection of Notch1 expression showed that the level of total Notch1 was very different in the examined tumor cell lines and this level was increased in all cell lines after treatment with the MO-I-1151 inhibitor." (PMID 38356711, 2024). "The Notch1 protein was produced in all the tumor cell lines examined, and its level was highly variable." (PMID 38817852, 2024). "Although no genes regulated through the Notch signaling pathway were significantly dysregulated, we found that NOTCH1 expression decreased significantly in ROS1+ tumor samples compared to RET+ specimens (p=0.04)." (PMID 39737401, 2024). "In this study, the role and mechanism of PD-L1 in tumor immune escape were explored, with particular focus on the promotion of IL-6 and IL-4 secretion by activation of the Notch-1/IRE1/XBP1s signaling pathway in macrophages." (PMID 38261741, 2024). "Triptonide, a natural small molecule extracted from Tripterygium wilfordii Hook F, efficiently inhibits tumor growth and metastasis via decreasing the levels of Notch1 downstream proteins RBPJ, IKK alpha, IKK beta, reducing p52 phosphorylation." (PMID 39092224, 2024). "NOTCH1 overexpression was found to have a time-dependent onset in clonal papillary tumors from a mouse model and induced tumor-like growth in human renal progenitor cells." (PMID 38791999, 2024). "Remarkably, VEGF and Notch1 dynamically interact at the cellular level to control the tumor’s ability to grow and regenerate, limitlessly." (PMID 38469406, 2024). "A higher percentage of intracellular portions of NOTCH1 (NICD)-positive cells were observed in tumor samples of KMT2Dmut patients than those of KMT2Dwt patients (p=0.044), indicating the link of KMT2D mutations with NOTCH signaling activation." (PMID 39113693, 2024). "Mechanistically, ANXA1 directly bound to the intracellular domain of Notch1 (NICD) to target this tumor suppressor for degradation." (PMID 39447086, 2024). "On the one hand, CHRNA5 can activate multiple signalling pathways, such as TGF-β1–Smad, JAK2/STAT3 and Notch1, thus promoting tumour cell proliferation, survival and metastasis." (PMID 38879667, 2024). "We validated the presence of metastatic lung xenografts by histological staining and confirmed an increased level of NOTCH1 protein in tumor-bearing mice with ALYREF overexpression compared to control conditions." (PMID 39117671, 2024). "NOTCH1 has been established as an oncogenic driver in several tumor models such as T-ALL, CLL, MCL, and a wide range of solid tumors, where activation recurs in different phases of the disease, both at diagnosis and relapse." (PMID 38255842, 2024). "Generally, Notch1 activation is known to promote cancer development, where as it can also play a tumor suppressor role." (PMID 38291201, 2024).
tumor (continued). "Consistent with the scRNA-seq data, the ectopic NRAS level tended to be higher in the NOTCH1/nestin+ tumours." (PMID 39112713, 2024). "In tumour therapy, the downregulation of Notch1 can achieve synergistic effects and reduce chemoresistance when targeted drugs are used alone or in combination with chemotherapy." (PMID 38405666, 2024). "Our results indicated that expression of Notch1 protein and its ligand Jagged1 were significantly higher in tumor tissue compared to normal surrounding tissue." (PMID 38866828, 2024). "Notch1 signalling is a versatile and evolutionarily conserved pathway that participates in tumour progression and carcinogenesis in various cancers." (PMID 38494478, 2024). "It is reported that in JAK3 mutation or NOTCH1-induced T-ALL, PHF6 deletion can significantly accelerate the development of the disease, indicating that PHF6 plays a tumor-inhibitory role in T-ALL." (PMID 38336746, 2024). "Notch1’s tumor suppressor activity is proposed to stem from its unique ability to counteract keratinocyte proliferation through one or more cell-autonomous signaling mechanisms." (PMID 39063983, 2024). "Knockout of TBC1D15, Notch1, or Notch2 alone or in combination was observed to reduce the tumor masses in these animals." (PMID 38409448, 2024). "Our findings identified a new molecular relationship between SOX2 and NOTCH1 in the context of drug resistance and tumor cell plasticity in TNBC." (PMID 39478150, 2024). "It is possible that tumor cells with aberrant Notch1 signaling acquire unidentified oncogenic functions, which lead to increased PD‐L1 expression in the nucleus." (PMID 38491819, 2024). "Regarding the gene expression of Notch1, P. crinita free extract (25, 50 mg/kg) groups significantly suppressed the change by (19.61%, and 48.04%, respectively), as relative to a tumor control group." (PMID 38469406, 2024). "The importance of the Notch-1 signaling system in controlling tumor biology is evident through its involvement in processes such as epithelial-mesenchymal transition (EMT), drug resistance, cell proliferation, differentiation, apoptosis, and metastasis." (PMID 38733531, 2024). "Studies have shown that an increase in Notch1 and Notch3 is associated with lower DFS in triple-negative and HER-2+ tumors while blockade of Notch 2 and 3 can reduce tumor growth and the frequency of tumor cell initiation." (PMID 39735530, 2024). "For instance, Notch1 inhibition within tumor and the subsequent hypersprouting leads to hypoxia and tumor growth reduction." (PMID 38984877, 2024). "In terms of tumours, studies have shown that abnormal activation of the Notch1 signalling pathway is related to the occurrence and development of a variety of diseases, such as tumour proliferation and metastasis and abnormal responses of the immune system." (PMID 38405666, 2024). "Infection with Human Cytomegalovirus (HCMV) induces the malignant transformation of tumor cells, sustaining stemness by upregulating Notch1 and NICD expression in U251 cells." (PMID 38672496, 2024). "Inhibition of Notch1 leads to hypersprouting and vessel dysfunction, increased hypoxia, and ultimately decreased tumor growth, but candidate therapeutics targeting Notch1 have exhibited significant toxicity in normal tissue." (PMID 38984877, 2024). "To assess the potential of our findings in addressing CSC‐mediated radiation resistance, we exposed PDOs to a single dose of 10 Gy radiation, resulting in a significant increase in the proportion of CD133‐positive tumour cells and Notch1 protein expression." (PMID 39523215, 2024). "Our study contributes to this understanding by examining the effect of ASPH inhibition on the Notch1 pathway in various tumor landscapes." (PMID 38817852, 2024). "Two of these genes (NOTCH1 and ARID1A) were each targeted by two mutational events in two different tumours." (PMID 39766052, 2024).
tumor (continued). "Selective Notch1 inhibition with a novel neutralizing monoclonal antibody developed in our laboratory not only exerts anti-tumor activity as a monotherapy, but importantly, boosts the therapeutic effects of anti-PD-1." (PMID 39491031, 2024). "Resveratrol can activate a protein called Notch-1, which has been shown to prevent tumor cell growth." (PMID 37111115, 2023). "STC1 and Notch1 signal formed a stromal-tumor amplifying feedforward signal in the TME, promoted HCC stemness, and provided new therapeutic targets for targeting both cancer cells and CAFs." (PMID 37004088, 2023). "Notch1′s association with tumor tissue was strongly linked to the TNBC subtype, elevated metastasis levels, tumor-node metastasis stages (TNM) and CSC cell surface receptor ALDH1." (PMID 36791960, 2023). "The NOTCH1 pathway forms a positive feedback loop between the tumor cells and TAMs, and its overexpression increases the expression of NOTCH1 and JAGGED1 and upregulates the expression of IL-1β and CCL2, thereby leading to M2 polarization." (PMID 37894541, 2023). "Given the context-dependency and pleotropicity of activated Notch signaling, NOTCH1 in CAFs has also been shown to have important tumor-promoting roles." (PMID 38269089, 2023). "Of note, expression of the lncRNA, LUNAR1, which displays T-ALL anti-tumor potential, was regulated by NOTCH1 through the IGF1R locus enhancer." (PMID 36674902, 2023). "Recent studies indicated that APOL1 exhibited oncogenic effects in PAAD, inhibiting PAAD cell apoptosis and promoting tumor cell proliferation through activation of the NOTCH1 signaling pathway, which was the first study reporting APOL1 function in PAAD." (PMID 37588985, 2023). "In summary, we found that CAF-secreted STC1 promoted HCC stemness and STC1 expression was positively related to Notch1 expression, poor prognosis, and advanced tumor stage in HCC." (PMID 37004088, 2023). "Accordingly, NOTCH1 signaling in CAFs has largely been shown to have a tumor suppressive effect with some reports indicating its pro-tumorigenic effect as well." (PMID 38269089, 2023). "The authors further identified a paracrine signaling between EC-expressing Dll4 and adjacent tumor cell-expressing Notch1, whose inhibition led to increased angiogenesis, with reduced vascular perfusions and demonstrated a potent anti-tumor effect." (PMID 38269089, 2023). "Although previously found to be involved in the induction of MenaINV expression in response to macrophage and tumor cell contact, Notch1 signaling alone was unable to induce MenaINV expression." (PMID 37024946, 2023). "In a transplantable mouse TNBC tumor model (C0321), SS had remarkable single-agent anti-tumor activity and eliminated Notch1 protein expression in tumors." (PMID 37901240, 2023). "Several reports demonstrate high frequency of loss-of-function mutations in Notch1 in HNSCC tumors, and consequently a tumor-suppressive role of Notch signaling in at least some subtypes of this disease." (PMID 37202533, 2023). "Recently, large‐scale analysis identified histone mutations in 3.8% of human tumor samples, a ratio similar to the mutations of known cancer‐associated genes such as BRCA2 and NOTCH1." (PMID 37255015, 2023). "FBXW7 is a main tumor suppressor due to its ability to control proteasome-mediated degradation of several oncoproteins such as c-Jun, c-Myc, Cyclin E1, mTOR, and Notch1-IC." (PMID 36934104, 2023). "MenaINV expression can be further enhanced by 2.5-fold when Notch1 is activated in addition to NF-κB in tumor cells." (PMID 37024946, 2023).
tumor (continued). "This study provides evidence that the newly developed potent small molecule, ASR490, explicitly suppresses Notch1 expression in BCSCs and BC by inhibiting cell proliferation and tumor growth in both in vitro and in vivo models." (PMID 36909163, 2023). "MDSCs-derived ROS can promote the proliferation and metastasis of circulating tumor cells by Nrf2/Notch1/Nodal signaling." (PMID 37646034, 2023). "The significant upregulation of the NOTCH1 target gene, Hes1, significantly increased the tumor volume, the positivity rate of tumor Ki67 staining, and lung metastasis in the subcutaneous xenograft mouse model." (PMID 36975516, 2023). "In this study, we showed that CSF2 induced the ubiquitination and downregulation of Notch1 in MSCs and their subsequent pro-tumor phenotype and function, indicating a critical role of Notch1 in the reprogramming of MSCs in cancer." (PMID 37865637, 2023). "These molecular alterations in epithelial ovarian tumours can be studied using immunohistochemistry (IHC) staining for Notch1 in the tumour cells, based on the various staining patterns and correlating the same with the grade and other parameters." (PMID 37489207, 2023). "Because NOTCH1 expression was associated with tumor differentiation, we then evaluated the combined effect of NOTCH1 expression and tumor differentiation on mortality." (PMID 37859809, 2023). "Collectively, these findings indicated that STC1 was regulated by Notch1 at the transcriptional level, generating an amplifying STC1-Notch1 feedforward signal in tumor-stromal crosstalk." (PMID 37004088, 2023). "We confirmed that the novel aberrant transcript isoforms result from focal genomic deletions that deleted multiple exons (in NOTCH1) or one exon (in RB1) from the tumor genome." (PMID 37553321, 2023). "Age, menstrual status, tumour laterality, gross appearance, histological features and Notch1 expression were the variables assessed." (PMID 37489207, 2023). "Endothelial-specific Sp1/Sp3 knockout reduces angiogenesis in retinal, pathological, and tumor models and induced activation of the Notch1 pathway." (PMID 36759621, 2023). "They showed that Notch1 overexpression drove cellular processes, such as tumour migration, invasion, proliferation and cell growth." (PMID 37762061, 2023). "Physical contact between macrophages and tumor cells results in the formation of ivadopodia via the Notch1/MenaINV signaling pathway in tumor cells." (PMID 37598126, 2023). "Targeting Notch1 signaling in vivo decreased NF-κB signaling activation and MenaINV expression in the primary tumor and decreased metastasis." (PMID 37024946, 2023). "We discovered here that the specific mechanism by which tumor cells acquire swift and sustained expression of the metastasis-inducing protein, MenaINV, is via macrophage-mediated cooperative NF-κB and Notch1 signaling." (PMID 37024946, 2023). "Thymoquinone downregulated Bcl-xL, Bcl-2, and XIAP and upregulated and activated pro-apoptotic molecules like caspases-3 and -9, Bax, cytochrome c release, inhibitory tumor growth, Notch1, NICD, PTEN, and Akt/mTOR/S6 signaling." (PMID 37958889, 2023). "Together our results indicate that ASR490 is a potential therapeutic agent that inhibits BC tumor growth by targeting and abolishing Notch1 signaling in BCSCs and BC cells." (PMID 36909163, 2023). "Our newly developed molecule, ASR490, is a selective Notch1 inhibitor that attenuates tumor growth in BCSC and BC models." (PMID 36909163, 2023).
tumor (continued). "This study provides a NOTCH1-targeted therapeutic aspect for cancer since senescent cells have been reported to be important for tumor progression." (PMID 38269089, 2023). "Notch1 and Notch3 signal transduction promotes tumor cell proliferation and inhibits apoptosis in certain NSCLC cell lines." (PMID 36644230, 2023). "We previously showed that MenaINV mRNA and protein expression in cancer cells involves macrophage-directed Notch1 signaling, and that macrophage expression of Jagged1 (a Notch signaling ligand) is critical for tumor cell intravasation." (PMID 37024946, 2023). "One tumor was positive for HPV45 and had mutations in FAT1 and FAT2; the other was positive for HPV31 and had mutations at NOTCH1, MAPK1, and HIST1H2AK." (PMID 38058352, 2023). "Tumor cells can also activate Notch1 signaling activity in ECs, leading to persistent Notch1 activation that facilitates tumor cell transmigration, intravasation, and metastasis." (PMID 37666809, 2023). "Notch activation triggers gastric stem/progenitor cell proliferation and GC tumor formation by activating the Notch1 and Notch2 receptors." (PMID 36768307, 2023). "NOTCH1 activity has both oncogenic as well as tumour-suppressive effects on cells during oncogenesis, depending on the tumour type." (PMID 37628760, 2023). "Previous work demonstrated that macrophages induce MenaINV expression in tumor cells through Notch1 signaling." (PMID 37024946, 2023). "The role of DLL4/Notch1 signaling in the development of the tumor vasculature has been studied extensively where it has been shown that Tip Cell formation, the initial cellular step of angiogenesis, is inhibited by DLL4–Notch signaling." (PMID 36376768, 2023). "Assessment of ASR490 treatment on Notch1 signaling in tumor tissue lysates showed significantly decreased Notch1-NICD and HES1 protein expression in the ASR490-treated groups compared to the vehicle-treated groups." (PMID 36909163, 2023). "Notch-1 was shown to have tumor-suppressive and oncogenic properties depending on inactivating or activating mutations." (PMID 37587308, 2023). "In contrast to the well-defined tumor-suppressive role of NOTCH1 in cancer, we identified overexpression of proteins involved in the Notch pathway, including NOTCH1." (PMID 37444412, 2023). "One study showed that low dose of IFNγ endowed tumor stemness in TME of NSCLC via regulation of ICAM1/PI3K/AKT/Notch-1 pathway, whereas high dose of IFNγ induced apoptosis of NSCLC cells via activation of JAK1/STAT1/caspase pathway." (PMID 37033636, 2023). "Single-cell data corroborated this finding, with significant increase in NOTCH1 expression in each tumour cell compared to normal human mesangial-like cells (Wilcoxon rank-sum test, p < 0.05)." (PMID 37749094, 2023). "Anti-NRR1.1E3 significantly reduced tumor size compared with control, indicating NOTCH1 signaling favors the growth of established lesions." (PMID 36658434, 2023). "Compared with the healthy tissues, the tumor tissues exhibited significantly elevated concentrations of arecoline and arecoline N-oxide and expression levels of a somatic protein (NOTCH1) and proinflammatory markers (IL-1β and IL-17)." (PMID 37190117, 2023). "Our studies here clearly demonstrate that in the murine skin at least, NOTCH1 has tumour suppressor function." (PMID 37626054, 2023). "Overall, these negative correlations reinforce the connection between DLL3 in the tumor microenvironment and NOTCH1." (PMID 37893184, 2023). "In their study, Wieland and others extensively describe the role of tumor endothelial cells Notch1 signaling in lung metastasis." (PMID 37887354, 2023).